KMT2D (lysine methyltransferase 2D)
Diseases named in the same sentence as KMT2D in open-access papers (continued):
Sharing a sentence is not in itself a finding about the gene and the disease.
tumor (continued). "Unlike KMT2A and KMT2B, KMT2C and KMT2D are known to impede cell proliferation and, oftentimes, are considered as tumor suppressors." (PMID 33302406, 2020). "We next analyzed tumors as a whole by categorizing each tumor as “positive” or “negative” for nuclear KMT2D using stringent criteria." (PMID 29950560, 2018). "Moreover, immunohistochemistry (IHC) identified loss of KMT2D protein expression in some tumors without detectable KMT2D-truncating mutations, suggesting that non-genetic causes of KMT2D inactivation may also occur in this tumor type." (PMID 29950560, 2018). "The close family members of KMT2A, KMT2C, and KMT2D also have negative effects on tumor cell growth, supporting the tumor-suppressive role of the KMT2 family." (PMID 28968975, 2017). "Epigenetic modifiers such as KMT2D, BCOR, METTL3 and METTL14 were a limiting factor for uncontrolled cell proliferation in 3D spheroids, which may reveal the mechanism of how they function as tumor suppressors in human cancer." (PMID 38853928, 2025). "To date, whether KMT2D is involved in the regulation of tumor macrophage polarization during NSCLC progression has not been reported." (PMID 40718439, 2025). "Lack of KMT2D sensitizes tumors to ICB via augmenting tumor immunogenicity." (PMID 39564571, 2024). "Furthermore, tumors lacking KMT2D present a blunt response to vitamin C in contrast to control group with a mild reduction in tumor weight." (PMID 39564571, 2024). "The decrease in KMT2D and resulting decrease in H3K4 triple methylation may provide an explanation of how Haspin is activated in PDA to facilitate histone H3 phosphorylation and tumor cell proliferation." (PMID 31719634, 2019).
cancer (179 papers, 2013 to 2026). A tumor composed of atypical neoplastic, often pleomorphic cells that invade other tissues. "For HPV-associated SNSCC with matched normal DNA the most frequently mutated COSMIC cancer driver genes included KMT2D (4/12 patients, 33%), FGFR3 and KMT2C (3/12 patients, 25%), GOLGA5, TET1, and ARID1B (2/12 patients, 16.7%)." (PMID 40500270, 2025). "Progression from LGASC to high-grade carcinoma is associated with additional pathogenic deletions in tumor suppressor genes such as KMT2D and BTG1, and loss of heterozygosity at 18q." (PMID 41301002, 2025). "Intriguingly, the loss of function of KMT2D, a histone methyltransferase, mediates genomic damage, thereby accelerating cancer progression." (PMID 39132156, 2024). "Gene set enrichment analysis (GSEA) showed that several crucial cancer hallmark signatures were enriched in KMT2D-KO SCC23 cells, including glycolysis, mTORC1 signaling, MYC targets, and ribosome biogenesis." (PMID 39117659, 2024). "They observed that L48H37 induces apoptosis through the ER stress-associated signaling pathway, with its anti-cancer effects enhanced by reduced KMT2D levels." (PMID 38791111, 2024). "TCGA database analysis by TIMER2.0 revealed that KMT2D is among the most frequently mutated genes in multiple cancer types." (PMID 39117659, 2024). "According to the database, among the KMT2A-D proteins, KMT2C is the most frequently mutated (~ 4 050 cases of cancer patients), followed by KMT2D (~ 2 600 cases), KMT2A (~ 1 580 cases), and finally KMT2B (~ 1 250 cases)." (PMID 36598580, 2023). "Missense variants in patients with KS and somatic variants in cancer showed an overlapping but also different distribution across KMT2D protein domains." (PMID 35856126, 2023). "We presented a comprehensive characterization of KMT2A, KMT2B, KMT2C, and KMT2D pathogenic variation in a large cancer‐free adult population, with ancestry‐ and sex‐specific frequencies." (PMID 36479909, 2023). "Genotype–phenotype correlations have been established between KMT2A (11q23.3), KMT2B (19q13.12), KMT2C (7q36.1), and KMT2D (12q13.12) somatic variants and different cancer types." (PMID 36479909, 2023). "KMT2D mutations have been recently found to sensitize cancer cells to aurora kinase inhibitors in HNSCC." (PMID 35664801, 2022). "Of chromatin modifiers, histone-lysine N-methyltransferase 2D (KMT2D) is among the most frequently mutated genes in multiple human cancers, including OSCC." (PMID 35477537, 2022). "As the largest H3K4 methyltransferase among them, KMT2D also represents the most frequently mutated gene in multiple human cancers, including OSCC." (PMID 35477537, 2022). "Although mutations in the SET domain of KMT2C and KMT2D are common in cancer (>25% of mutations), mutations are also found in other domains, including the PHD domains." (PMID 35406676, 2022). "Mutations in the KMT2D gene are common in cancer patients, and their deficiency can increase the levels of genomic DNA damage and TMB, as well as increase transcription instability." (PMID 36479108, 2022).
cancer (continued). "The epigenetic regulator MLL4 (KMT2D) is considered an essential gene in both human and mice and is one of the most frequently mutated genes across all of human cancer." (PMID 34890228, 2021). "The KMT2 family member KMT2D, which regulates the H3K4me methylation landscapes predominantly at enhancers, has been implicated in the development of cancer by dysregulation of enhancer activity and subsequent disruption of normal development programs." (PMID 34834500, 2021). "KMT2D has been defined as one of the most commonly mutated genes in a number of cancers such as gastric cancer, lymphoma and medulloblastoma." (PMID 33805950, 2021). "KMT2C and KMT2D histone lysine methyltransferases are among the most frequently mutated genes across a variety of cancer types." (PMID 33381456, 2020). "There are no integration sites in chromosomes 21, 22, and X. Only five genes of the many associated with MCPyV integration, namely SF3B1, TLX3, CD74, MYC, and KMT2D, are cancer-linked genes listed in the COSMIC database." (PMID 32878339, 2020). "For example, mixed-lineage leukemia protein 2/histone-lysine N-methyltransferase 2D (MLL2/KMT2D), a histone-modifying enzyme that interacts with the AR, was mutated in 8.6% of cancers." (PMID 27408704, 2016). "We found that a KMT2D deficiency resulted in attenuated cancer cell proliferation and defective cell migration." (PMID 24240169, 2013). "Notably, several studies demonstrated that KMT2D deficiency has great therapeutic potential in various cancer types." (PMID 39117659, 2024). "Mutations of APOB, USH2A, and KMT2D were reported to be associated with poor prognosis in several cancer types, and could be considered targets for combination therapy." (PMID 38922489, 2024). "KMT2D is one of the most frequently mutated genes across various types of cancers." (PMID 39117659, 2024). "Given the prevalence of mutations across cancers, exploration on the molecular behavior of KMT2D may bring broad implications for patient stratification." (PMID 39564571, 2024). "KMT2D is one of the most frequently mutated genes in human cancers." (PMID 37142882, 2023). "KDM6A, KMT2D, and p300 are important proteins implicated in cancer and developmental syndromes." (PMID 37410700, 2023). "The mutation of epigenetic regulator KMT2D was a biomarker of poor prognosis in some cancers." (PMID 35265613, 2022). "It has been proposed that patients with germline variants in KMT2D may be at an increased risk for developing cancer due to somatic second hit mutations." (PMID 36292647, 2022). "For other types of cancer, the clonality of KMT2D mutations remains to be investigated." (PMID 34194626, 2021). "Loss of function of the H3K4 methyltransferase KMT2D is also frequently observed in cancers." (PMID 34109280, 2021). "In order to further determine the function of two candidate genes CTNNB1 and KMT2D, and locate potential cancer-associated genes that may play a key role in cell proliferation, we used an short hairpin RNA (shRNA)-mediated loss-of-function screening method." (PMID 33968779, 2021). "More recently, genes encoding KMT2D proteins have been implicated in many cancers." (PMID 34758724, 2021). "The genes encoding KMT2C (MLL3) and KMT2D (MLL4) are among the most frequently mutated in cancer." (PMID 32471474, 2020). "The linkage of KMT2D to enhancer elements here provides a critical step toward understanding its regulatory mechanisms and its association to various types of cancers, as enhancer elements play essential yet diverse roles in cell type-dependent gene transcription." (PMID 24240169, 2013). "To clarify the role of KMT2D in cancer cells, we employed somatic gene knockout approaches to generate a panel of isogenic KMT2D-deficient human cancer cell lines and determined the impact of a KMT2D deficiency on neoplastic cells." (PMID 24240169, 2013). "Furthermore, a higher KMT2D expression was associated with a poor prognosis in this cancer type." (PMID 33302406, 2020).
cancer (continued). "MLL2, also known as KMT2D (Lysine Methyltransferase 2D), of which mutation is a driver in numerous different cancer types resulting in transcription stress and genome instability, and a recent study demonstrated that MLL2 could sustain prostate carcinogenesis and metastasis." (PMID 31293963, 2019). "In particular, HMucBOT-2 demonstrated copy number gains in chromosomes 5 and 12 where KRAS, KMT2D, and CLIP1 are located and have been associated with cancer transformation." (PMID 40427213, 2025). "Inhibition of ITGAL abrogated KMT2D overexpression-mediated M1 macrophage polarization and its anti-cancer effects on NSCLC." (PMID 40718439, 2025). "The ITGAL knockdown counteracted KMT2D-mediated M1 macrophage polarization and its anti-cancer effects on NSCLC." (PMID 40718439, 2025). "The cancer-associated genes PTEN (7%), KMT2C (7%), KMT2D (7%), RB1 (6%), and CREBBP (4%), were again among the 15 most frequently mutated and at similar frequencies as observed in CALGB 40603." (PMID 40057511, 2025). "Other notable mutated cancer-related genes include PIK3CA (7%), CREBBP (6%), KMT2C (6%), KMT2D (6%), RB1 (5%), PTEN (5%), and FAT1 (5%), all of which are reported as “Tier 1” cancer-related gene mutations in the COSMIC Cancer Gene Census21." (PMID 40057511, 2025). "Multiple HKMTs, including EZH2 and KMT2D, have been reported to play critical roles in cancer progression." (PMID 41203594, 2025). "The presence of histone methyltransferases such as KMT2D reinforces previous findings linking epigenetic dysregulation and cell cycle control to cancer progression." (PMID 41035678, 2025). "Crucially, pan-cancer analyses indicate that KMT2D alterations represent not only a potential biomarker for predicting prognosis and immunotherapy response but also a key immune regulatory factor in human malignancies." (PMID 40895533, 2025). "Using the essentiality network mapping functions in GRETTA, we compared the fitness effects of KMT2D knockout (KO) to the effects of knocking out 18,333 genes that were screened by DepMap in 739 cancer cell lines across > 30 cancer types." (PMID 39578878, 2024). "Pan-cancer analysis found that KMT2D is significantly upregulated in AML, AML is a major blood stem cell disease." (PMID 39867575, 2024). "Several studies found that cancers harboring mutations in the components of the COMPASS-like complex, including KDM6A, KMT2C, and KMT2D, were associated with poor differentiation and aggressive behavior." (PMID 38791111, 2024). "When mutations of KMT2D decrease methylation at H3K4, genes that suppress the Notch pathway are repressed, leading to the development of cancers like medulloblastoma (MB)." (PMID 39765675, 2024). "The clonally unrelated RT, RT-1 which harbors a GC phenotype, showed the presence of MYD88, a CLL driver mutation, as well as mutations in genes implicated in cancer pathogenesis, TET2 and KMT2D, which have also been seen in RT." (PMID 39246801, 2024). "To explore the role of KMT2D in HNSCC, we first examined the genetic alterations of KMT2D in various cancer types." (PMID 39117659, 2024). "For instance, the methylation of H3K4 by KMT2D, the most frequently mutated HMT across many cancer types, weakens the interactions of histone with DNA, allowing the genes in this region to become activated." (PMID 39765675, 2024). "In order to investigate the immunological role of KMT2D in cancer environments, the estimated values of KMT2D in pan-cancer were calculated." (PMID 39867575, 2024).
cancer (continued). "The histone methyl transferase encoding gene KMT2D, also known as MLL2 and MLL4, is also mutated in various cancers." (PMID 38786098, 2024). "They employed pooled mutagenic screening within CRISPR-mediated genetically engineered mouse models specifically designed for ICB settings, which enabled the identification of KMT2D as a pivotal modulator of ICB response across multiple cancers." (PMID 38791111, 2024). "Our data showed that KMT2DLOF alterations were associated with lower KMT2D protein expression so, from this, we infer that KMT2D activities are reduced or lost in most cancer types, as expected." (PMID 39578878, 2024). "Put it all together, these shreds of evidence are highly suggestive of its involvement in the pathogenesis of the disease, but considering its antithetical effects on cancers, more studies are needed to clarify the exact influence of KMT2D on ATLL." (PMID 36841815, 2023). "Mutations in epigenetic modifier enzymes KMT2B, KMT2C, KMT2D, and ARID1A were more prevalent in MSI cancers, where the majority possessed KMT2B and KMT2D mutations and over one-third had KMT2C and ARID1A mutations (χ2 test p = 0.001)." (PMID 37998722, 2023). "Four cancer driver genes, namely KMT2D, LRP1B, TRRAP, and FLNA, were identified in the 20 most frequently mutated gene sets." (PMID 37373553, 2023). "The most frequent mutations in a large panel of 1123 cancer-related genes in the overall population of RCC patients were VHL (51%), PBRM1 (35%), BAP1 (16%), KMT2D (15%), PTPRD (15%), and SETD2 (15%)." (PMID 37427096, 2023). "For a detailed discussion about the (in vitro) oncogenic potential of KMT2D and its role in cancer we refer to recent articles and reviews." (PMID 35856126, 2023). "Through pan-cancer analysis, we discovered the differential expression of KMT2D between many cancers and normal tissues." (PMID 35281840, 2022). "Of the six Compass complexes that can methylate H3K4, KMT2A/MLL1, KMT2C, and KMT2D (MLL3 and 4) have been most widely implicated in cancer." (PMID 35406676, 2022). "Reportedly, KMT2D collaborates with the SWI/SNF complex to promote cell type-specific enhancer activation, and cancer cells with KMT2C deficiency have higher endogenous DNA damage and genomic instability." (PMID 36371186, 2022). "Changes and failure to express KMT2D and ZHX3 respectively are associated with cancer development, and a significant increase in cell growth after suppressing both is consistent with these functions." (PMID 36580499, 2022).